GCG (glucagon)
Diseases named in the same sentence as GCG in open-access papers (continued):
Sharing a sentence is not in itself a finding about the gene and the disease.
Hypoglycemia (continued). "Urgent treatment is required when severe hypoglycemia occurs and can be effectively reversed by injection of glucagon, which can be administered intravenously, intramuscularly, or subcutaneously." (PMID 33042005, 2020). "The physiological values of glucagon in hypoglycemia are markedly reduced, whereas unphysiologically high glucagon levels are observed in hyperglycemia, which is a hallmark of T2DM." (PMID 33327428, 2020). "Mini-doses of SC glucagon are efficient in treating milder hypoglycaemia in children as well as in adults, and the glucose rising effect is the same regardless of hypoglycaemic or euglycaemic BGL4." (PMID 32792580, 2020). "While insulin promotes cells absorbing glucose, thus reducing blood glucose levels to prevent hyperglycemia, glucagon signals for the release of stored glucose from the liver, resulting in increased blood glucose levels to prevent hypoglycemia." (PMID 32993686, 2020). "GIP, like GLP-1, allows for the increase of the insulin secretion and inhibition of the glucagon discharge, emphasizing this by stimulating the secretion of glucagon during hypoglycemia." (PMID 32131470, 2020). "The objective of this case series review was to assess the potential clinical utility of dose-titrated glucagon infusion regimens to achieve glycemic stability, and prevent hypoglycemia in patients with CHI." (PMID 33013678, 2020). "Dextrose treats the hypoglycemia, provides energy substrate required for metabolism, and stimulates insulin secretion while suppressing glucagon secretion." (PMID 32560535, 2020). "Our study demonstrates the efficacy of continuous IV glucagon in the management of hypoglycemia due to CHI." (PMID 33013678, 2020). "In general, the body has protective mechanisms to prevent hypoglycemia during a period of energy shortage that includes lowering serum insulin levels and stimulating glucagon, cortisol, epinephrine, and growth hormone secretion." (PMID 32560535, 2020). "Embedded in this modulation environment, pancreatic beta cells secrete the only hormone that lowers glucose in hyperglycemia (insulin, equimolarly with c peptide), and pancreatic alpha cells secrete a contra-regulatory hormone in hypoglycemia (glucagon)." (PMID 33510648, 2020). "Glucagon secreted from pancreatic α-cells is the principal glucose-elevating hormone counteracting hypoglycemia by stimulating glucose production in the liver." (PMID 32156704, 2020). "Fortunately, the role of glucagon was revealed in studies on exercising men when somatostatin was given to block glucagon secretion and hypoglycemia resulted." (PMID 32785124, 2020). "On the other hand, at low glucose, ATP can drop below the level required for glucagon secretion, thus leading to failure of glucagon counterregulation and hypoglycemia." (PMID 32774668, 2020). "When glucagon secretion is impaired, the adrenergic mechanism, especially adrenomedullary adrenaline, is essential for recovery from hypoglycemia." (PMID 32235382, 2020). "On the other hand, several recent studies in liver suggest a role for glucagon that extend beyond the prevention of hypoglycemia and into the control of nutrient metabolism during the fed state." (PMID 32964214, 2020). "After gastric bypass, there is a marked decrease in levels of glucagon, cortisol, and catecholamine in response to hypoglycemia." (PMID 33371340, 2020). "Furthermore, increasing workout intensity and duration also elicits a greater epinephrine response inducing counter-regulatory mechanisms such as glucagon release and increased hepatic glucose output, which may elevate blood glucose and glucose variability, or cause hypoglycemia." (PMID 31396757, 2020). "With the addition of titrated glucagon, hypoglycemia was arrested in all patients, who demonstrated plasma glucose concentrations ranging between 3.5 and 10.0 mmol/L." (PMID 33013678, 2020).
Hypoglycemia (continued). "We previously generated GCGR knockout zebrafish that display hypoglycemia, hyperglucagonemia, and compensatory α-cell hyperplasia, demonstrating that the function of glucagon signaling is at least partially conserved between humans and zebrafish." (PMID 31979106, 2020). "Among patients with hypoglycaemia, 2.8% were treated with glucagon and 91.6% with glucose and/or glucose solution i.v. in the emergency room." (PMID 32429960, 2020). "In healthy individuals, glucose increases ATP to promote glucagon secretion in hypoglycemia and to suppress glucagon secretion at higher glucose levels to prevent hyperglycemia." (PMID 32774668, 2020). "CGM Alone followers reported 2 episodes of severe hypoglycemia interventions (administration of glucagon or calling emergency services), once at 8–12 weeks and once at 20–24 weeks gestation, while CGM Share followers reported none." (PMID 32298269, 2020). "We extensively reviewed the evidence of the CB being implicated in the regulation of blood pressure and glucose metabolism, acting on the counterregulatory responses to hypoglycemia and mediating insulin/glucagon secretion." (PMID 32698380, 2020). "The study improves our understanding of how a decline in mitochondrial bioenergetics is linked with the typical hormonal disorders in T2DM: a decreased insulin secretion, and in-/decreased glucagon secretion in hyper-/hypoglycemia, respectively." (PMID 33327428, 2020). "Despite the rapid effects of glucagon and catecholamines on glucose regulation, the effects of cortisol and growth hormone during hypoglycemia are delayed." (PMID 32187262, 2020). "We show that in the absence of paracrine influence, isolated α-cells respond appropriately to hypoglycemia with an increase in glucagon granule exocytosis." (PMID 32312960, 2020). "Exogenous glucagon stimulates hepatic autophagy, and during conditions of increased endogenous glucagon secretion, such as starvation, hypoglycemia, and type 1 diabetes, the number of hepatic lysosomes is increased." (PMID 33333850, 2020). "Nevertheless, the potential use of glucagon for treating patients with PBH was tested using low-dose closed-loop infusion pumps that demonstrated to reduce the rates of hypoglycemia and prevent rebound hyperglycemia." (PMID 33424773, 2020). "In our case series, titrated glucagon was successful as an adjunct in the stabilization of glucose concentrations and prevention of hypoglycemia while reducing dependence of high volumes of dextrose containing fluid." (PMID 33013678, 2020). "Glucagon, secreted by the pancreatic α-cells, has long been studied under the perception that it has the primary role of raising blood glucose to prevent hypoglycemia." (PMID 32964214, 2020). "Specifically, a 30–40% reduction in alpha cells’ mitochondrial function leads to a pathological shift of glucagon secretion, characterized by oversecretion at high glucose concentrations and insufficient secretion in hypoglycemia." (PMID 33327428, 2020). "RIP-GLUT1/GLUT2 mice display normal postprandial blood glucose levels but fasting hypoglycemia, glycosuria, and an elevated glucagon-to-insulin ratio." (PMID 32591906, 2020). "The recently proposed bi-hormonal AP system controls both insulin and glucagon pump to reduce hypoglycemia while maintaining intensive insulin treatment, and thus does not require carbohydrate counting by patients." (PMID 31694629, 2019). "Remarkably, the MTII treatment improved counterregulatory responses to hypoglycemia in the diabetic mice by augmenting the stimulation of epinephrine and glucagon release compared to the diabetic mice that received PBS." (PMID 30503832, 2019). "The authors suggested that nasal glucagon can be used as a rescue treatment for severe hypoglycemia but noted unavoidable side effects that included itching of the eyes, throat, and nasal lining." (PMID 31052466, 2019).
Hypoglycemia (continued). "We report a human factors validation program evaluating the glucagon autoinjector (GAI) (Gvoke HypoPenTM; Xeris Pharmaceuticals, Inc., Chicago, IL) versus marketed glucagon emergency kits (GEKs) for managing severe hypoglycemia." (PMID 31219349, 2019). "The 30-min prediction horizon enabled an acceptable accuracy while providing an effective time for correcting hypoglycemia with carbohydrate ingestion or injection of glucagon." (PMID 31694629, 2019). "Glucose, insulin and somatostatin exert inhibitory effects on alpha cell secretion of glucagon, whereas hypoglycemia and amino acids are known to stimulate the secretion of glucagon." (PMID 31443356, 2019). "These are the body's response to hypoglycemia by release of counter regulatory hormones like glucagon, epinephrine and cortisol which can be treated by altering type and time of meal and medication." (PMID 31080251, 2019). "Of interest is the evidence that, among insulin-treated patients, the frequency of access to emergency department because of hypoglycemia was lower for patients with prescribed glucagon than that of other patients." (PMID 31349701, 2019). "Despite treating the hypoglycemia supportively with multiple boluses of 25 g of dextrose, a continuous dextrose infusion, and glucagon, the patient experienced repeated episodes of rebound hypoglycemia." (PMID 31210993, 2019). "Hypoglycemia was confirmed by a 6‐hr fasting test, which was followed by an inappropriately large glycemic response (delta 73 mg/dl) to a pharmacologic dose of glucagon." (PMID 31464105, 2019). "When eating only meat, GIP presumably allows the insulin levels to rise enough to store the fat and protein and the glucagon levels to rise enough to prevent hypoglycemia." (PMID 31781045, 2019). "Fortunately, glucagon emergency kits are easily available, and those in close contact with a person prone to hypoglycemia should be instructed on how to administer glucagon." (PMID 31138204, 2019). "Although this increase was to a lesser extent in diabetic subjects, the glucagon levels observed nonetheless reached the concentrations exhibited by healthy participants to hypoglycemia during the placebo study." (PMID 30696060, 2019). "In adults, severe hypoglycaemia is defined as any episode of hypoglycaemia requiring the assistance of a third party to actively administer carbohydrate, glucagon, or take other corrective actions." (PMID 31655586, 2019). "During the 1970s and the 1990s, there were concerns about failures of treatment of hypoglycemia with the remedies available at that time, i.e., IV dextrose and IM glucagon." (PMID 31349701, 2019). "On the other hand, the glucagon response to hypoglycemia is completely lost in T1D patients, and after recurrent hypoglycemia the impaired plasma epinephrine response is improved with naloxone infusions." (PMID 31013147, 2019). "Additional research comparing this training to the standard teaching content on hypoglycemia is needed to determine if the interactive hypoglycemia and glucagon training is more effective in educating students and impacting patient outcomes." (PMID 31138204, 2019). "The catecholamines such as epinephrine and norepinephrine play an important part in countering hypoglycemia especially if glucagon release is impaired." (PMID 31275775, 2019). "Glucagon, the insulin counter regulatory hormones plays an important role in preventing hypoglycemia, particularly when the body receives an insulin-stimulating agent under fasting conditions." (PMID 31404283, 2019). "Treatment of hypoglycemia is still based on administration of carbohydrates (oral or parenteral according to the level of consciousness) or of glucagon (intramuscular (IM) or subcutaneous (SC) injection)." (PMID 31349701, 2019).
Hypoglycemia (continued). "We therefore conclude that the therapy with both insulin and glucagon performs better than the therapy with only insulin, as the risks for both hypoglycemia and hyperglycemia are reduced and glucose fluctuations are suppressed." (PMID 30893335, 2019). "Most stated that they learned practical information, such as how to treat hypoglycemia and administer glucagon." (PMID 31138204, 2019). "Ultimately, the metabolism of glucagon hinges upon the concentration of glucose, either by direct secretion during hypoglycaemia, or indirectly via insulin-mediated inhibition during hyperglycemia." (PMID 31829209, 2019). "Results showed that glucagon counter-regulation during hypoglycemia is sustained during DPP-4 inhibition." (PMID 31275243, 2019). "Glucagon’s rapid effect to stimulate hepatic glucose production renders glucagon a valuable emergency medication for the treatment of acute severe hypoglycemia." (PMID 31671603, 2019). "Ablation of these VMH SF1 neurons impairs the recovery from insulin-induced hypoglycemia, while their activation, under normoglycemic conditions, raises blood glucose levels by increasing glucagon secretion and inhibiting glucose-stimulated insulin secretion." (PMID 31072002, 2019). "Nonetheless, glucagon has gained little pharmacological attention outside its role to rescue hypoglycemia." (PMID 31671603, 2019). "Combined these findings point toward endogenous insulin playing a key role in preventing hypoglycaemia; perhaps directly by stopping secretion when blood glucose levels fall or indirectly through counter‐regulatory hormones such as glucagon." (PMID 30955221, 2019). "For these patients it has been proposed that exogenous insulin can be used to lower their blood glucose level and exogenous glucagon can be used to prevent hypoglycemia." (PMID 30893335, 2019). "It is further evident that type 1 diabetics with an impaired response to glucagon would be unable to raise their blood glucose levels and would require an infusion of glucose to recover from hypoglycemia." (PMID 31829209, 2019). "Stimulation of epinephrine and glucagon release in response to hypoglycemia or glucopenia was diminished in both POMC- and MC4R-deficient mice, relative to their littermate controls." (PMID 30503832, 2019). "Previous studies have provided evidence that Ca2+ is a main trigger of exocytosis in alpha cells, and alpha cells show electrical activity and Ca2+ signalling in the presence of low glucose concentrations that stimulate glucagon release in hypoglycaemia." (PMID 30953108, 2019). "The epinephrine response following sympathetic neural activation is critical in T1D patients and is due to islet cell failure and the subsequent inability to increase glucagon levels after hypoglycemia." (PMID 31013147, 2019). "Like the ArcPomc−/− mice, the Mc4rPVH-knockdown mice manifested reduced circulating epinephrine and glucagon following hypoglycemia." (PMID 30503832, 2019). "Although a previous study showed that the glucagon secretion was unresponsive to intravenous infusion of fructose during hypoglycemia in healthy subjects, we found a postprandial increase in glucagon levels after the intake of the OFTT in T1DM patients." (PMID 31365624, 2019). "Treatment of hypoglycemia is still based on administration of carbohydrates (oral or parenteral according to the level of consciousness) or of glucagon (intramuscular or subcutaneous injection)." (PMID 31349701, 2019). "The potent regulation of glucagon secretion by glucose from isolated perfused pancreas preparations supports a direct effect of hypoglycemia on the alpha cell, unless stimulatory neurons of the intra-pancreatic ganglia are glucose sensitive." (PMID 31284506, 2019). "In the context of these findings, we have demonstrated the significance of hypothalamic POMC alone in hypoglycemia counterregulation including stimulation of the release of epinephrine and glucagon." (PMID 30503832, 2019).
Hypoglycemia (continued). "The primary physiological counterregulatory response to hypoglycemia includes rapid increases in plasma epinephrine and glucagon levels." (PMID 30503832, 2019). "Circulating glucagon levels are thus low in the prandial state (~10 pmol/L in humans) and increase 2–3 fold in response to long-term fasting or hypoglycemia." (PMID 31671603, 2019). "In the early 60’s, an intravenous (i.v.)insulin pump delivering insulin and glucagon to counteract hypoglycemia was reported by Kadish (1964)." (PMID 32232090, 2018). "The insulin‐dose resulting in hypoglycemia was increased four times: from 40 nmol/kg insulin alone to 160 nmol/kg insulin in the presence of the glucagon‐analogue." (PMID 29595915, 2018). "Glucagon responses were normal in conditional brain glucokinase-knockout mice, suggesting that glucagon release during hypoglycemia is controlled by glucokinase-mediated glucose sensing outside the brain but not in β-cells." (PMID 30146176, 2018). "If hypoglycaemia is detected, the system activates automatically the treatment module that reacts by glucagon injection." (PMID 30568801, 2018). "Where glucagon is concerned, sex-related differences seem to exist only where individuals have experienced hypoglycemia prior to exercise." (PMID 30524371, 2018). "e. decreased glucagon secretion in response to hypoglycemia, and fasting hyperglucagonemia with inadequate plasma glucagon decrease in response to meals." (PMID 29352311, 2018). "Driven by the protective effect of dual treatment with insulin and glucagon on hypoglycemia, we went on to determine the optimal ratio between the two hormones." (PMID 29595915, 2018). "A combination of MPC and PID was used to drive a dual-hormone AP system that added glucagon to combat hypoglycemia." (PMID 32232090, 2018). "The decline in function appears to happen evenly across the sexes, resulting in similar glucagon responses to exercise and to hypoglycemia at rest." (PMID 30524371, 2018). "Hypoglycemia awareness (the ability to recognize symptoms of low blood glucose) is limited, and glucagon and epinephrine response to hypoglycemia (the endocrine defense mechanism to correct low blood glucose) are blunted in the elderly." (PMID 29460258, 2018). "Hypoglycemia prompts an integrated response involving reduction in insulin release and secretion of key counter-regulatory hormones glucagon and epinephrine that together promote endogenous glucose production to restore normoglycemia." (PMID 30146176, 2018). "Plasma glucagon levels were highly increased in infected Adx mice with hypoglycemia, suggesting that pancreatic α-cells reacted correctly to the low glycemia." (PMID 30375380, 2018). "The sympathoadrenal response to hypoglycaemia also stimulates glucagon release, and intra-islet glucose levels affect glucagon production as well." (PMID 29412829, 2018). "Taken together, these data are consistent with direct GCK-mediated sensing of hypoglycemia by α-cells being an important part of the counter-regulatory glucagon response." (PMID 30146176, 2018). "Nevertheless, our results suggested that the blunted responses of glucagon and epinephrine participated in the deterioration of the hypoglycemia in SstCreR26DTA mice." (PMID 29880854, 2018). "Here, we found that increased glucagon responses to hypoglycemia persisted in I366F mice following β-cell ablation, suggesting that local paracrine signalling from pancreatic β-cells was not necessary to mediate effects of mutant GCK." (PMID 30146176, 2018). "For example, the hepato-portal vein region contains glucose sensitive nerve terminals that can control glucagon secretion as indicated by the fact that portal vein glucose infusion can suppress hypoglycemia-induced increase in plasma glucagon." (PMID 32232085, 2018). "Twenty-three neonates with HI had a glucagon test (1 mg IM or IV) showing blood glucose response > 30 mg/dl following hypoglycemia." (PMID 29723237, 2018).